PAX5 (paired box 5)
Diseases named in the same sentence as PAX5 in open-access papers (continued):
Sharing a sentence is not in itself a finding about the gene and the disease.
cholangiocarcinoma (1 paper, 2022). A carcinoma that arises from the intrahepatic biliary tree (intrahepatic cholangiocarcinoma) or from the junction, or adjacent to the junction, of the right and left hepatic ducts (hilar cholangiocarcinoma). "Accordingly, PAX5-induced PSMA3-AS1 boosted occurrence and development of cholangiocarcinoma via mediating miR-376a-3p/LAMC1." (PMID 35022330, 2022). "The present research uncovers that PAX5/PSMA3-AS1/miR-376a-3p/LAMC1 expedites cholangiocarcinoma deterioration, and PSMA3-AS1 is hopeful to become an intervention target for cholangiocarcinoma." (PMID 35022330, 2022).
chronic GVHD (1 paper, 2024). "In the human setting, one study found greater numbers of B cells expressing PAX5 in the bone marrow of patients who did not develop chronic GVHD (as compared with patients who did)." (PMID 39207851, 2024).
co-infection (1 paper, 2020). "Few studies carried out on samples of pediatric patients diagnosed with cHL have identified PAX5 expression and EBV co-infection." (PMID 32604737, 2020).
Constitutional mismatch repair deficiency syndrome (1 paper, 2021). "Germline PAX5 and ETV6 mutations carry a high risk (high penetrance) of cancer, mainly ALL7, 9, 27; bloom syndrome and constitutional mismatch repair deficiency syndrome also carry a moderate risk of ALL." (PMID 33903686, 2021).
ductal carcinoma in situ (1 paper, 2017). "More specifically, we observed Pax-5 expression in: 93% in normal breast; 100% in all invasive ductal and lobular carcinoma; 86% in mucinous adenocarcinoma; and, 100% of ductal carcinoma in situ." (PMID 28076843, 2017).
enterokinase deficiency (1 paper, 2025). "PAX5 P80R subtype showed significantly expressed TMPRSS15 involved in enterokinase deficiency." (PMID 41246237, 2025).
eosinophilia (1 paper, 2024). "In addition, eosinophilia and PAX5 rearrangement (PAX5::GSDMA and PAX5::ZCCHC7) have also been found, as well as the observation of a hyperdiploid karyotype with a structural alteration." (PMID 38254826, 2024).
granuloma annulare (1 paper, 2026). Granuloma annulare is a long-term (chronic) skin disease consisting of a rash with reddish bumps arranged in a circle or ring. "In this article, we present a case of granuloma annulare with a pseudolymphomatous B-cell component (PAX5+, CD79+) and minimal T-cell involvement, observed in a 4 mm skin nodule located on the shoulder of a 48-year-old male." (PMID 42200821, 2026).
hairy cell leukaemia (1 paper, 2023). "Based on CD 20, PAX5, and CD 79b, a possible diagnosis of hairy cell leukaemia was made and annexin A1 IHC was recommended because it was not available in our hospital's setup." (PMID 37538441, 2023).
head and neck squamous cell carcinoma (1 paper, 2022). A squamous cell carcinoma that arises from any of the following anatomic sites: lip and oral cavity, nasal cavity, paranasal sinuses, pharynx, larynx, and salivary glands. "Additionally, methylation of PAX5 has been characterized as a tumor-specific event in head and neck squamous cell carcinoma." (PMID 36077495, 2022).
hemophagocytic lymphohistiocytosis (1 paper, 2025). "Turbinate biopsy revealed tumor cells localized predominantly within vascular lumens, positive for CD20, BCL6, PAX5, and MUM1, with a Ki-67 index >60%, confirming a diagnosis of IVLBCL with hemophagocytic lymphohistiocytosis(HLH)." (PMID 41407466, 2025).
Hernia (1 paper, 2017). "To explore this hypothesis, we analyzed the presence of macrophages and B lymphocytes within the hernia, by measuring immunoreactivity against CD68(ED1) and Pax5, respectively." (PMID 28297581, 2017). "Surprisingly, we found an increase in Pax5+ B lymphocytes in situ in the hernia, but CD68+ macrophages were not altered between groups." (PMID 28297581, 2017).
ileocolitis (1 paper, 2026). Ileocolitis or ileal Crohn's is the most common type of Crohn's disease. "Biopsies revealed severe active ileocolitis with ulceration and an atypical EBV-positive B cell proliferation (CD20/PAX5+, MUM1+, variably CD30+, EBV-LMP1+; polytypic light chains)." (PMID 42287555, 2026).
Immunodeficiency (1 paper, 2025). Failure of the immune system to protect the body adequately from infection, due to the absence or insufficiency of some component process or substance. "PAX5 deficiency: The germline variants in PAX5 show an AD inheritance pattern with incomplete penetrance; consequently, patients may be asymptomatic, develop immunodeficiency, or B-ALL." (PMID 40722698, 2025).
insulinomas (1 paper, 2023). "Still, it is noteworthy that the interobserver agreement in scoring PAX5 positivity on RSC and CB was similar to that reported for scoring endocrine cytoplasmic immunomarkers in small tissue samples (tissue microarrays) of canine insulinomas." (PMID 36851461, 2023).
leprosy (1 paper, 2025). Leprosy is a chronic infectious disease affecting primarily the skin and peripheral nervous system. "The mean rank differences observed in Dunn's multiple comparisons test delineate distinctions in the ratio of double-labeled positive cells in comparison to single-positive PAX5 or CD20 cells per unit area among distinct leprosy groups." (PMID 40784052, 2025).
mesothelioma (1 paper, 2021). A usually malignant and aggressive neoplasm of the mesothelium which is often associated with exposure to asbestos. "Moreover, in non-small cell lung cancer (NSCLC), mesothelioma and oesophageal cancer, the expression of PAX5 was also decreased." (PMID 33397394, 2021).
metastatic lymph node tumors (1 paper, 2016). "The aberrant expression of PAX5 has been found to be associated with metastatic mammary carcinoma, and the gene has much higher expression in metastatic lymph node tumors." (PMID 27625789, 2016).
Nephroblastoma (1 paper, 2025). An embryonal neoplasm characterized by the presence of epithelial, mesenchymal, and blastema components. "Positive staining for neuroendocrine markers (NSE, synaptophysin, chromogranin A) and negative staining for lymphoid (CD3, Pax5) and nephroblastoma (WT1) markers were pivotal in confirming the tumor’s neuroendocrine origin." (PMID 40948633, 2025).
NK/T cell lymphoma (1 paper, 2022). "One case was extra-nodal NK/T cell lymphoma (EBER+), and the other four cases were DLBCL (CD20+, PAX5+)." (PMID 35067228, 2022).
otitis (1 paper, 2021). "The levels of expression of BLIMP-1 and XBP1 were significantly lower in patients who were prone than those who were not prone to otitis, whereas expression of BCL6 and PAX5 tended to be higher in the otitis-prone group." (PMID 33801155, 2021).
otitis media (1 paper, 2021). Inflammation of the anatomical structures of the middle ear, which is most often caused by an infectious process. "B cell leukemia/lymphoma-6 (Bcl-6) and paired box gene 5 (Pax-5) suppress antibody production, whereas B lymphocyte inducer of maturation program 1 (Blimp-1) and X-box binding protein 1 (XBP-1) promote antibody production during immune responses in patients with otitis media." (PMID 33801155, 2021).
pc (1 paper, 2021). "Unlike CHL, PAX5 is rarely expressed in pc-ALCL, but the transcriptional factor MUM1/IRF4 is positive in most cases of pc-ALCL." (PMID 34572893, 2021).
periodontitis (1 paper, 2023). An acute or chronic inflammatory process that affects the tissues that surround and support the teeth. "Furthermore, EN1 regulates FCER2A, which is also overexpressed in periodontitis via the regulation of PAX5, up in the disease." (PMID 37834287, 2023). "Even though we identified this TF in our analyses as a component of module 1 in our GRN, and confirmed that it is directly regulated by PAX5, a component of our periodontitis context-specific GRN, it surprisingly did not meet our criteria for being considered a master regulator." (PMID 37834287, 2023).
renal calculi (1 paper, 2024). "By analyzing the differential expression in pediatric renal calculi, we identified four differentially expressed genes: CTCFL, MYH11, MyoD1, and PAX5." (PMID 39242558, 2024).
rheumatoid arthritis (1 paper, 2014). A chronic, systemic autoimmune disorder characterized by inflammation in the synovial membranes and articular surfaces. "It is a stromal cell line-derived glycosylphosphatidylinositol-anchored molecule that has been identified to facilitate pre-B-cell maturation based on its enhanced expression in rheumatoid arthritis-derived bone marrow stromal cell lines and activation by Pax5." (PMID 24780490, 2014).
sarcopenia (1 paper, 2023). Progressive decline in muscle mass due to aging which results in decreased functional capacity of muscles. "We supposed that PAX5-SERPIAN5-PI3K/Akt axis is a potential mechanism in sarcopenia, and B cells may also play a vital role in this signal transduction." (PMID 37525094, 2023). "Since it has also been proposed to have a major role in the development and renewal of neurons, PAX5 may also have a close relationship with neuromuscular junction disorders in sarcopenia." (PMID 37525094, 2023). "We hypothesized that PAX5-SERPIAN5-PI3K/Akt axis is a potential mechanism in sarcopenia and that B cells may play a vital role in this signal transduction." (PMID 37525094, 2023). "Consistent with the literature, we found that PAX5 and SERPINA5 were positively correlated with muscle function and that their expression levels were significantly reduced in sarcopenia." (PMID 37525094, 2023). "Among the four DETFs, only PAX5 exhibited significantly decreased expression, while TP73, BCL11A and TFAP2C were increased in sarcopenia." (PMID 37525094, 2023). "In this study, we investigated the relationship between the PAX5-SERPINA5-PI3K/Akt axis and sarcopenia for the first time." (PMID 37525094, 2023).
Sepsis (1 paper, 2025). Sepsis is defined as life-threatening organ dysfunction caused by a dysregulated host response to infection. "Our results suggest that myeloid cells that arise during sepsis may secrete Aβ, suppressing B cells by inhibiting Pax5 and Ciita expression in an endocrine/paracrine manner." (PMID 40185975, 2025).
skin melanomas (1 paper, 2021). "Many of them were previously appreciated in the genome of skin melanomas (e.g., MITF, NOTCH2, PD-L1 and JAK2 amplifications, or CDKN2A deletions); however, the CNAs in genomic locations harboring PAX5, ETS1, BCL7, RAD51, APAF1, FOXO3 and CTNNA1 are novel." (PMID 33779796, 2021).
T-lymphoblastic lymphoma (1 paper, 2022). The most frequent type of lymphoblastic lymphoma. "When reconstructed by insertion of a PAX5 mini gene into the mouse Igh locus, these mice develop aggressive T-lymphoblastic lymphomas instead of B-ALL, probably because of the expression of PAX5 throughout the lymphoid system as a germline mutation rather than as somatic mutations in patients." (PMID 36387144, 2022).
thymoma (1 paper, 2016). A neoplasm arising from the epithelial cells of the thymus. "Consultant review of the excised mediastinal mass showed scattered large atypical cells that were CD20+ and PAX-5+ and negative for pan-cytokeratin, AE1, and AE3, compatible with THRLBCL and excluding thymoma." (PMID 26904321, 2016).
transitional cell carcinomas of the bladder (1 paper, 2017). "Others have also shown that the presence of Pax-5 in transitional cell carcinomas of the bladder is associated with a fourfold relative risk of malignancy." (PMID 28076843, 2017).
tumor (209 papers, 2006 to 2026). "The PAX5/ETV6 fusion protein acts as a promoter of leukemic B-cell activation, unlike deletions or point mutations that result in an inactivated form of PAX5, classifying it as a tumor suppressor." (PMID 40506992, 2025). "Its specific role in B-cell maturation makes PAX5 a highly specific marker of the B-cell lineage and incorporating it into a panel of immunohistologic markers for investigating undifferentiated neoplasms provides diagnostic benefits." (PMID 40506992, 2025). "Low miR-24 expression was previously associated with a diminished tumor-suppressor effect of miR-31 and PAX5 (paired box 5 protein) deletion." (PMID 36010971, 2022). "The observed oligoclonal origin of the Pax5Jak2/+ B‐ALL tumors furthermore suggests that rare independent events of Pax5 loss by uniparental disomy were strongly selected for cell expansion to contribute to tumor development." (PMID 35156727, 2022). "The nonsynonymous somatic variants detected in TBL1XR1 and PAX5 were all regarded as major clonal variants, i.e., present in the majority of tumor cells." (PMID 35205758, 2022). "Of note, Ikzf1, Spi1, Tcf3, and Pax5 are normally expressed in induced B cell progenitors, which ensure tumor-free lymphopoiesis as reduction or loss of any of these master factors is associated with B cell leukemia." (PMID 34893754, 2022). "Some studies have found paired box gene 5 (PAX5) promoter methylation in GC cells and tumor tissues that was significantly associated with the survival of GC patients, which is consistent with our findings of PAX5 and its related Wnt signaling pathway in GC." (PMID 36561311, 2022). "So far, the effect of mutations in PAX5 enhancer was studied only in CLL where the associated decrease in PAX5 expression suggests a tumor suppressor role of PAX5." (PMID 34210001, 2021). "By sequencing the integrations of B ALL samples, recurrent truncating mutations were observed in Ebf1, a tumor suppressor of B ALL which encodes a transcriptional activator of another B cell ALL tumor suppressor Pax5." (PMID 34484175, 2021). "Chromosome 9p contains numerous tumor-associated genes, such as PAX5 at 9p13.2, CDKN2A, CDKN2B, MTAP, IFN, MLLT3, PTPLAD2 at 9p21.3, and JAK2 at 9p24.1." (PMID 31168295, 2019). "Expression levels of direct transcriptional targets in PAX5 mutated (PAX5M) samples were compared to normal PAX5 (PAX5WT) tumor samples." (PMID 31381561, 2019). "The 4.6-fold reduced expression associated with CRE mutation is consistent with PAX5 functioning as a tumor suppressor in MM, as in other B-cell malignancies." (PMID 29654271, 2018). "The downregulation of tumor suppressors PAX5 and HOXB3 by CRE mutations in MM is entirely consistent with their decreased expression contributing to development and progression of MM as is the case with other B-cell malignancies." (PMID 29654271, 2018). "To determine the clinical relevance of association of YMO1, RhoC and PAX5 in cancer invasion and metastasis, we validated the experimental results in tumor tissues derived from 153 HCC patients in training cohort." (PMID 27487132, 2016). "Thus, we next performed whole exome sequencing (WES) of paired tumor and germline samples from Pax5+/− tumors to study the status of the wild-type Pax5 allele within PD-1+ leukemic cells." (PMID 41283237, 2025). "The consistent loss of the wild‐type Pax5 allele in Pax5Jak2/+ tumor cells raised the question of whether the full‐length Pax5 protein may interfere with the function of Pax5‐Jak2." (PMID 35156727, 2022). "Altogether, given its pro-epithelialization role in breast tumors, PAX5 suppresses invasive properties leading to better prognostic value with a lower risk of disease progression and relapse as long as cancer cells remain in their primary tumor sites (in situ)." (PMID 36077495, 2022). "Loss of PAX5 could be expected to create a more aggressive tumor." (PMID 28484276, 2017).
tumor (continued). "PAX3, PAX5, and PAX8 are mainly associated with immune checkpoint expression, including PD-L1 and TIGIT, while PAX6 is linked to microsatellite instability and tumor mutational burden, implicating it in genomic dysregulation." (PMID 41752124, 2026). "In this case, the tumor cells expressed CD79a and PAX-5, along with high expression of c-Myc and Bcl-2, which closely resembled the characteristics of “double-expressor DLBCL” in terms of pathological morphology." (PMID 41561755, 2025). "To identify somatically acquired second hits leading to B-ALL development in Pdcd1fl/fl;Mb1-Cre;Pax5+/− mice, we performed whole-genome sequencing of paired tumor and germline samples from two Pdcd1fl/fl;Mb1-Cre;Pax5+/− tumors." (PMID 41283237, 2025). "Our 2 cases highlight the potential value of CD3 and PAX5 immunohistochemical markers in ophidians and expand the spectrum of neoplastic diseases documented in reptiles." (PMID 40359093, 2025). "The CD11b+ cells are reported to respond to the M-CSF produced by tumor cells and downregulate the expression of Pax5, allowing them to transdifferentiate into macrophages." (PMID 40486046, 2025). "PAX5 has been shown to act as a tumor suppressor in the B-lymphoid lineage and haploinsufficiently synergize with Stat5b-CA to induce ALL in mice." (PMID 39469218, 2024). "To identify somatically acquired second hits leading to B-ALL development in Pax5+/−;Myd88+/− mice, we performed whole-genome sequencing of paired tumor and germline tail DNA samples from eight Pax5+/−;Myd88+/− tumors." (PMID 37620322, 2023). "The spontaneous downregulation of Pax5 in cancer cells led to a myeloid phenotype, while enforced Pax5 expression produced a lymphoid-like tumor." (PMID 38022639, 2023). "In vivo, the PAX5-overexpressed and miR-142-delepted cells were subcutaneous injected into SCID mice, and it was observed that the tumor volumes were notably decreased by PAX5 over-expression and increased by miR-142-5p/3p-deletion." (PMID 37403081, 2023). "To confirm that high Pax5 expression in tumor tissue actually originates from the epithelial cells/NE-like cancer cells, we further analyzed single cell RNA-sequencing data published recently (GSE137829)." (PMID 38168280, 2023). "GADD45B-high tumor cells showed strong associations with transcription factors such as ELK1, PAX5, SMAD3, BACH1, and NR1H2." (PMID 37608794, 2023). "Univariate analysis indicated the patients with stages III-IV, B symptoms, tumour recurrence, PAX5 positivity, and c-MYC positivity showed a shorter survival time (p<0.05)." (PMID 36634942, 2023). "PAX5 functioned as a tumor suppressor by positive regulation of miR-142-5p/3p both in vitro and in vivo." (PMID 37403081, 2023). "As reference tumors, we analyzed B‐ALLs that developed in the lymph nodes of Pax5+/−Cdkn2ab+/− mice, a tumor model that lacks constitutively activated JAK‐STAT signaling." (PMID 35156727, 2022). "Master regulators of hematopoietic lineages have been implicated in tumor suppressor function, as reported for C/EBPα and SPI1/PU.1 in acute myeloblastic leukemia (AML) or PAX5 loss of function in B-ALL." (PMID 35401501, 2022). "We also determined the lineage contribution of the tumor cells by staining for PAX-5 (B cells), myeloperoxidase (MPO) (myeloid cells), and CD3 (T cells) (56, –, 58)." (PMID 35852337, 2022). "In this review, we provide an overview of the reported data describing PAX5 products, their regulation, and function in cellular processes, cellular biology, and neoplasm." (PMID 36077495, 2022). "The study then experimentally validated that miR-181a, miR-217, and miR-1275 represent the most impactful tumor suppressors lost during PAX5 3′UTR shortening in cancer cell models." (PMID 36077495, 2022). "In all brain samples, most of the tumor-associated lymphocytes inside the tumor were CD3+ T-lymphocytes, with only a few dispersed Pax-5+ B lymphocytes." (PMID 36419904, 2022).